EPHB4 (EPH receptor B4)
Diseases named in the same sentence as EPHB4 in open-access papers (continued):
Sharing a sentence is not in itself a finding about the gene and the disease.
cancer (continued). "Future elucidation of the specific role of this newly described ubiquitin–ligase complex towards controlling EphB4 protein levels may provide novel molecular agents and targeting strategies towards down-modulation of the pathological effects associated with EphB4 in cancer and human disease." (PMID 37108544, 2023). "Taken together, our results emphasize the role of EphB4 as a suppressor of cancer cells’ intrinsic metastatic capacity, which can be amplified by agents that activate EphB4." (PMID 39489818, 2025). "EPHB4 is believed to be actively involved in promoting cancer cell growth and deterioration in these types of cancers." (PMID 40842575, 2025). "EphB4 and ephrinB2 are a receptor-ligand pair that has been heavily studied for their role in metastasis across numerous cancer types." (PMID 39489818, 2025). "EphB4 inhibition in cancer cells also amplifies their ability to metastasize through increased expression of genes associated with hallmark pathways of metastasis along with classical and non-classical epithelial-mesenchymal transition." (PMID 39489818, 2025). "While E-cadherin downregulation and vimentin upregulation are hallmarks of classical EMT, we observed opposite trends upon knockout of cancer cell EphB4 in vitro and in vivo." (PMID 39489818, 2025). "We observed that EphB4 knockout cancer cells had increased migratory capacity compared to control cells in vitro." (PMID 39489818, 2025). "Our findings revealed that EphB4 knockdown in cancer cells polarizes CD4+ T cells towards the Treg phenotype and enhances Treg immunosuppression." (PMID 39091728, 2024). "The EphB4-ephrinB2 signaling axis is aberrantly expressed in a variety of cancers, highlighting it as a promising therapeutic target." (PMID 39091728, 2024). "Taken together, our results emphasizes the role of EphB4 as a suppressor of cancer cells’ intrinsic metastatic capacity, which can be amplified by agents that activate EphB4." (PMID 39091728, 2024). "To further investigate the effect of EphB4 on cancer cell migration, we employed Transwell Boyden chamber assays." (PMID 39091728, 2024). "Knockdown of EphB4 in cancer cells combined with radiation treatment promotes suppressive intratumoral immune populations." (PMID 39091728, 2024). "EphB4 inhibition in cancer cells also amplifies their ability to metastasize through increased expression of genes associated with epithelial mesenchymal transition and hallmark pathways of metastasis." (PMID 39091728, 2024). "Nefl also induces apoptosis, suppresses growth, and decreases invasion of HNSCC cancer cells, offering potential mechanisms by which Nefl downregulation in EphB4 knockout cancer cells enhances their metastatic capacity." (PMID 39091728, 2024). "Our findings indicate that knockdown of EphB4 in cancer cells leads to increased metastasis in two models of HPV-unrelated HNSCC due to multiple factors." (PMID 39091728, 2024). "Collectively, these results suggest that EphB4 knockout induces molecular changes in MOC2 cancer cells, affecting regulation of the cytoskeleton, migration, and EMT." (PMID 39091728, 2024). "Building upon our RNAseq and mass spectrometry proteomics data, we used flow cytometry analysis to further understand the implications of cancer cell EphB4 knockdown in vivo." (PMID 39091728, 2024). "Additional results revealed that EphB4 contributes to increased proliferation, motility, and migration of cancer cells." (PMID 39839790, 2024). "Specifically, we illuminate the role of EphB4 knockdown in cancer cells, shedding light on its impact on metastatic potential and the immune microenvironment." (PMID 39091728, 2024). "We observed that EphB4 knockdown cancer cells had increased migratory capacity compared to control cells in vitro." (PMID 39091728, 2024). "Further investigation will eventually clarify the dynamic interactions and molecular events linking IGFII/IRA upstream signaling to EphB4 and the contribution to its biological effects in the cancer cell." (PMID 37108544, 2023).
cancer (continued). "This strategy, if adopted at the therapeutic level, simplifies the current approach aiming to block EphB4 cancer-promoting effects through inhibitor compounds requiring membrane translocation towards intracellular targeting of the EphB4 RTK activity." (PMID 37823054, 2023). "The binding pattern of the factors identified with EphB4 herein is consistent with their direct involvement in the observed IGF-II/IRA signal-mediated regulation of EphB4 protein levels in the studied cancer cell line." (PMID 37108544, 2023). "Neutralization of cancer secreted IGF-II in these cells (a) blocked EphB4 Y987 phosphorylation, (b) increased EphB4 ubiquitination, and (c) associated with rapid and marked EphB4 protein clearance." (PMID 37443713, 2023). "EphB4 is an erythropoietin receptor (EPO) and has proved to associate with drug resistance of cancer cells in human chronic myeloid leukemia and prostate cancer." (PMID 37174034, 2023). "The confirmation of a tight functional dependence for EphB4 protein expression in malignant mesothelioma along with a number of cancer cell lines bearing the IGF-II autocrine signal raised the question on the underlying mechanism." (PMID 37823054, 2023). "In contrast, knockdown of EphB4, particularly its intracellular domain, increases cancer cell viability, enhances VEGF secretion, and angiogenesis." (PMID 35725568, 2022). "The knockdown of EphB4 and ephrinB2 on the cancer cell was confirmed by co-immunofluorescence staining between EpCAM and EphB4 or ephirnB2." (PMID 35725568, 2022). "EPHB4 activation can promote cancer growth, migration and metastasis by activating downstream signaling pathways including the RAS/MEK/ERK and EPHB4/RHOA pathways." (PMID 35689424, 2022). "Data on the implications of EphB4 and ephrinB2 expression and cancer progression have been conflicting depending on the disease site." (PMID 35725568, 2022). "Another observation evident after downregulation of EphB4 on cancer cells was the significant decrease in the influx of CD8 + T cells." (PMID 35725568, 2022). "Since the RNA-sequencing data suggested that EphB4 knockdown on cancer cells also affected angiogenic markers, we determined the effects of EphB4 cancer cell knockdown on the vascular TME by CD31 immunohistochemical (IHC) staining." (PMID 35725568, 2022). "We also observed increased p-SHP1 levels on western blotting following cancer cell EphB4 knockdown compared to the control tumors." (PMID 35725568, 2022). "A significant increase in VEGF levels was detected in the conditioned media of both EphB4 knockout cells and EphB4 dominant-negative cancer cells compared to their respective controls." (PMID 35725568, 2022). "Differential outcomes of EphB4-ephrinB2 signaling offers formidable challenge for the development of cancer therapeutics." (PMID 35725568, 2022). "Activation of EphB4 induces cell migration and invasion in cancer cells, although the exact opposite effect has also been reported." (PMID 35273957, 2022). "More importantly, the authors have provided positive data for the efficacy of vandetanib as a potential strategy against cancers with high‐EPHB4 expression." (PMID 35689424, 2022). "Similar to CUHN013 cells, our data showed a significant increase in cancer cell growth in the Moc2 EphB4 KO group compared to the control group." (PMID 35725568, 2022). "For example, EphB4 is overexpressed in many cancers such as colon, lung, ovarian, prostate, breast, melanoma, endometrial, and pancreatic cancers which is associated with tumor development." (PMID 35046810, 2021). "Exerted anti-cancer activities by aggravating mitochondrial impairment and ER stress through EphB4/CDC42/N-WASP signaling." (PMID 34026649, 2021). "The coexpression of Ephrin-A3 can block the ability of EphA2 and EphA3 to link ephrins in trans and become activated, while Ephrin-B2 can deter not only EphB4 but also EphA3 in the cancer cells." (PMID 32368295, 2020).
cancer (continued). "Examples include Eph‐dependent signalling in endocrine and immune systems as well as in cancer cell proliferation, where links between EphB6 and EphA10 and canonical kinases such as EphB4, EphB1 and Src‐family kinases have been established." (PMID 32053275, 2020). "A peculiar example of the role of isoform switch by the insulin receptor signaling with direct possible implications on cancer malignant transition regards the regulation of EphB4 protein levels in cancer cells by the autocrine IGF-II/IR-A signaling axis." (PMID 33266015, 2020). "Hsa_circ_0002375, hsa_circ_0111974, and hsa_circ_0081534 are spliced from KIT ligand (KITLG), estrogen related receptor gamma (ESRRG), and EPH receptor B4 (EPHB4), respectively, which play an essential role in cancer proliferation, metastasis and apoptosis." (PMID 32426279, 2020). "EphB4 expression is elevated in a variety of human cancers, including cancers of the head and neck, ovaries, lung, and esophagus." (PMID 32733636, 2020). "Studies on the expression of EphB4 in numerous cancer types have shown overexpressed level in breast, colorectal, lung, and blood cancers correlating with poor prognosis." (PMID 32801343, 2020). "Both forward and reverse signaling by the EphB4/ephrinB2 interaction is context-dependent and can vary from one cancer type to another." (PMID 32850441, 2020). "Although most of these targets are supported by immunohistochemical studies for various types of cancer, very few if any of these targets are evaluated in T/N comparisons, like shown here for EphB4." (PMID 32751634, 2020). "The demonstration of EphB4 cancer-promoting effects in a variety of malignant cancer types has provided the rational for targeting EphB4 as a mean to block its reverse signaling in the therapeutic setting." (PMID 31270394, 2019). "Although the EphB4 cancer-promoting effects have been established, little is known about the exact mechanisms by which EphB4 exerts such effects." (PMID 31270394, 2019). "Several reports have shown EPHB4 overexpression in various cancers including those of the prostate, breast, colon, head and neck, and lung." (PMID 31641103, 2019). "A possible scenario for the EphrinB2-independent EphB4 cancer-promoting effects come from the observation that EphB4 is able to bind and eventually trans-activate other membrane TK receptorial systems such as the EGFR." (PMID 31270394, 2019). "The observed inverse trend between the IGFII self-stimulation status and EphB4 ubiquitination observed in the in vitro assay was also shown for the endogenous/native EphB4 pool from the same cancer cells using ELISA." (PMID 31270394, 2019). "Another member of the Eph receptor family belonging to the B class, EphB4, has also been found to be upregulated in multiple cancer types." (PMID 28165374, 2017). "The specific binding of the final nanoparticles with EphB4-positive cancer cells and their targeted accumulation into subcutaneous xenograft and orthotopic tumors were investigated in detail." (PMID 28942682, 2017). "An EphB4-mediated cancer cell killing effect was investigated by incubating the co-culture system of SKOV3/A549 cells with HP-TCS followed by the measurement of cell survival." (PMID 28942682, 2017). "The flow cytometry data, performed with polyclonal antibodies against whole proteins rather than internal domains, indicated that EphA2 is at least as abundantly present on living cancer cells as EphB4." (PMID 28165374, 2017). "Eph receptors are also able to activate the Rho pathway to regulate cancer cell migration and thus it is possible that EphB4 and integrin β8 work cooperatively to control cell motility." (PMID 25886373, 2015). "Most commonly, the EphB4/ephrin-B2 balance in many cancer cells is disrupted by over-expression of the EphB4 receptor." (PMID 25831049, 2015).
cancer (continued). "We used a peptide exclusion approach to identify an epitope within the extracellular cysteine-rich domain of EphB4 that is targeted by a commercially available polyclonal antibody with in vitro anti-cancer effects." (PMID 25831049, 2015). "This is consistent with reports from the literature that describe anti-cancer effects of EphB4 antibodies targeting other epitopes." (PMID 25831049, 2015). "This shows that the H200 antibody targets the hallmark roles EphB4 plays in cancer, justifying use of monoclonal antibodies for the development of new therapies against EphB4 positive cancers." (PMID 25831049, 2015). "EphB4 over-production promotes ligand-independent signaling pathways that increase cancer cell viability and stimulate migration and invasion." (PMID 25831049, 2015). "EPHB4 on the other hand has been shown to be transcriptionally regulated by HoxA9 in endothelial cells, but no information is available about the transcription factors involved in regulating expression of EPHB4 in cancer cells." (PMID 25886373, 2015). "Correspondingly, knockdown of EphB4 in several cancer cell lines consistently resulted in a 70–80% reduction in cancer cell viability, an 8–16 fold increase in apoptosis and up to an 80% reduction in cell migration and invasion." (PMID 25831049, 2015). "An EphB4-specific polyclonal antibody, targeting a region of 200 amino acids in the extracellular portion of EphB4, showed potent in vitro anti-cancer effects measured by an increase in apoptosis and a decrease in anchorage independent growth." (PMID 25831049, 2015). "With roles in regulating/modifying the important cancer progression hallmarks of viability, migration and invasion and common over-expression in up to 82% of epithelial cancers, EphB4 is a key target for the development of anti-cancer therapies." (PMID 25831049, 2015). "It is this dichotomy of EphB4 signaling that makes this receptor tyrosine kinase a unique target for the development of anti-cancer therapies." (PMID 25831049, 2015). "Knockdown experiments using cell lines representing several of these epithelial cancers have shown that EphB4 increases cancer cell viability, and contributes to migration and invasion." (PMID 25831049, 2015). "Amplification of the EphB4 gene has also been reported in clinical samples and cell lines from several cancer tissues including prostate, breast, bladder and head and neck." (PMID 25831049, 2015). "Knockdown experiments using EphB4 targeting siRNA sequences have shown that EphB4 contributes to cancer cell viability, migration and invasion identifying the key roles for EphB4 in cancer cells." (PMID 25831049, 2015). "Among the Eph receptors, EphA2 and EphB4 are the most widely expressed in epithelial and cancer cells, although most other Eph receptors including EphA3 are also aberrantly expressed in at least some cancers." (PMID 24348920, 2013). "EphB4 has also been reported to play an oncogenic role in cancers of the head and neck, prostate, other genitourinary organs, breast, mesothelium, esophagus, skin, and large bowel." (PMID 23844053, 2013). "Positive staining in the cell membrane of the cancer cells has been shown for both EphB4 and ephrinB2." (PMID 18231102, 2008). "EphB4 as well as ephrinB2 histoscores in cancer cells correlated with the corresponding mRNA levels in each case (EphB4, P<0.001; ephrinB2, P<0.001)." (PMID 18231102, 2008). "Role of EphB4-ephrin-B2 in androgen deprived mice was tested for role in refractory cancer model." (PMID 40044981, 2025). "To investigate whether EphB4 enhances metastasis through a canonical cancer-cell centered mechanism, we explored intrinsic changes induced by loss of EphB4 in the cancer cell using RNA sequencing." (PMID 39489818, 2025). "Our data suggests that targeted inhibition of vascular ephrinB2 while avoiding inhibition of EphB4 in cancer cells could be a promising strategy to mitigate HNSCC metastasis." (PMID 39489818, 2025).
cancer (continued). "Comparison of transcriptomic changes between MOC2 control and EphB4 knockout cell lines showed higher expression of TGF beta receptors 1 and 2, NOTCH1, and FOXC1, a transcription factor implicated in cancer cell plasticity, treatment resistance, invasion, and epithelial-mesenchymal transition (EMT)." (PMID 39091728, 2024). "Knockdown of EphB4 in HNSCC cancer cells promotes distant metastasis." (PMID 39091728, 2024). "Our data suggest that targeted inhibition of vascular ephrinB2 while avoiding inhibition of EphB4 in cancer cells could be a promising strategy to mitigate HNSCC metastasis." (PMID 39091728, 2024). "OEDR regulation of EphB4 by the IGF-II/IR axis in Cancer: first of a new kind?" (PMID 37823054, 2023). "EPHB4 has become important components of various cancer treatment strategies." (PMID 35689424, 2022). "Cancer cell knockdown of EphB4, on the other hand, yields an influx of immunosuppressive Tregs." (PMID 35725568, 2022). "EphB4 is shown to be upregulated in a variety of human cancers, including head and neck cancers." (PMID 35725568, 2022). "EphB4, on the other hand, was predominantly expressed in the cancer cells." (PMID 35725568, 2022). "We screened different cancer entities for the expression of EPHB4 and EFNB2." (PMID 35629359, 2022). "Similarly, the addition of conditioned media from either EphB4 knock out cancer cells or dominant-negative EphB4 transfected cells increased the vascular network formation." (PMID 35725568, 2022). "Although EphB4 activation was evident with the administration of ephrinB2-Fc, no additional growth inhibitory effects were observed when ephrinB2 is knocked out either on the vasculature alone or on both the cancer cell and the vasculature." (PMID 35725568, 2022). "Some reports suggested that berberine drives EphB4 inhibitory activity on cancer cell growth." (PMID 35046810, 2021). "Pharmacologically targeting EphB4 has emerged as a strategy against numerous cancers." (PMID 32850441, 2020). "EPHB4 is one of the EphB subfamily, the largest of receptor tyrosine kinases, which is known to facilitate vascularization in multiple carcinomas and is upregulated in various cancers, including upper aerodigestive cancers." (PMID 32426279, 2020). "Furthermore, we included the family member EphB4 because its overexpression has also been reported in various cancer types." (PMID 28165374, 2017). "Addition of H200 to cancer cells in vitro causes a decrease in EphB4 gene expression identifying a negative feedback loop." (PMID 25831049, 2015). "EphB4 meets all of these characteristics in many cancer cell lines used as models of different epithelial cancers making it an ideal target for the development of new monoclonal antibody-based anti-cancer therapies." (PMID 25831049, 2015). "EphB4 and EphrinB2 are expressed in adult life and are required for the development/maturation of newly forming vessels only, and thus represent targets for modulation of angiogenesis including cancer." (PMID 25148033, 2014). "Here we show that in cancer cells, coexpressed ephrin-A3 can inhibit the ability of EphA2 and EphA3 to bind ephrins in trans and become activated, while ephrin-B2 can inhibit not only EphB4 but also EphA3." (PMID 24348920, 2013). "Both EphB4 and ephrinB2 mRNA seemed to be expressed mainly from the cancer cells." (PMID 18231102, 2008). "Collectively, these results provide an association between the absence of EphB4 and cancer cell polarization towards a pro-metastatic phenotype, as EphB4 knockout induces molecular changes in MOC2 cancer cells that affect regulation of the cytoskeleton, migration, and non-classical EMT." (PMID 39489818, 2025). "Given the observed increase in Tregs with EphB4 knockdown in the cancer cell, we investigated whether CD4+ T cells within the TME differentiate into Tregs by treating CD4+ T cells with conditioned medium from MOC2 EphB4 knockdown cancer cells in vitro and conducting flow cytometry." (PMID 39091728, 2024).